INS (insulin)
Diseases named in the same sentence as INS in open-access papers (continued):
Sharing a sentence is not in itself a finding about the gene and the disease.
Insulin resistance (continued). "The aim was to investigate mechanisms by which betaine improves hepatic insulin signaling in a dietary mouse model of insulin resistance and fatty liver." (PMID 39119463, 2024). "This leads to the secretion of pro-inflammatory cytokines, which have the potential to induce insulin resistance, affecting both local and systemic insulin sensitivity." (PMID 39606781, 2024). "Lutein supplementation in rats fed with a high-fat diet (HFD), a model of MASLD, recovered liver function, improved lipid accumulation, and restored hepatic lipid metabolism and insulin signaling, preventing hepatic dyslipidemia and insulin resistance." (PMID 38978979, 2024). "FAHFAs can target G-protein-coupled receptors 40 and 120 to promote insulin secretion and relieve insulin resistance, with decreased levels in obese individuals." (PMID 39220365, 2024). "Hepatic insulin resistance is characterized by impaired insulin signaling in the liver, leading to increased glucose production and decreased glycogen storage, all of which contribute to hyperglycemia." (PMID 38967989, 2024). "In the context of insulin resistance, IL-6 interferes with insulin signaling pathways by activating serine kinases, such as c-Jun N-terminal kinase (JNK), which phosphorylate insulin receptor substrate proteins and disrupt insulin receptor signaling." (PMID 38044678, 2024). "Both glucose tolerance tests and insulin tolerance tests indicated insulin resistance in LBW goat kids compared to controls (p < 0.05)." (PMID 38596462, 2024). "Collective insulin levels to get rid of hyperglycemia induced by pathway-selective insulin resistance which is likely to activate insulin signaling pathways that are non-resistance in nature, including MAPK (Mitogen-activated protein kinase)." (PMID 39674630, 2024). "In the present study, there was a noteworthy change in insulin, insulin resistance, TG, and PAB levels in the intervention and control groups compared to the baseline." (PMID 39430281, 2024). "Based on our results and the referenced literature, we propose that increased chain splitting of endogenous insulin prior to insulin receptor activation—throughout the body or locally—is a direct mechanism of in vivo insulin resistance." (PMID 40604313, 2024). "Fasting glucose and insulin, Homeostatic Model Assessment-Insulin Resistance (HOMA-IR), glucose and insulin area under the curve, Surrogate Hepatic Insulin Resistance Index, Matsuda ISI, Predicted M ISI, and Stumvoll Index were assessed." (PMID 38201980, 2024). "Adipokines such as leptin, resistin, and retinol-binding protein 4 increase insulin resistance, whereas adiponectin with anti-inflammatory and antilipogenic effects increases insulin sensitivity." (PMID 39065815, 2024). "For instance, when a high-fat diet was used to induce insulin resistance, other authors have reported that IR deletion in SMCs decreases the neointimal area, suggesting a growth-promoting effect of insulin in vascular SMCs." (PMID 39195275, 2024). "Lastly, mitochondrial dysfunction affects the oxidation of fatty acids, leading to the accumulation of lipid intermediates, further disrupting insulin signaling pathways and resulting in insulin resistance." (PMID 39280009, 2024). "Specifically, enriched GO terms such as ‘hormonal response regulation’ and ‘glucose homeostasis’ suggest potential mechanistic links to disrupted insulin signaling pathways, a hallmark of MASLD characterized by lipid metabolic disorder and insulin resistance." (PMID 38755697, 2024). "Mice fed with BCAAs exhibited elevated expressions of phosphorylated mTORSer2448, phosphorylated S6K1Thr389, and phosphorylated IRS1- Ser302, which can induce changes in insulin signaling, resulting in insulin resistance." (PMID 38931292, 2024). "Increased triglycerides were correlated with impaired glucose metabolism in muscle tissue and inhibited insulin signalling pathways, leading to insulin resistance." (PMID 39881810, 2024).
Insulin resistance (continued). "The HOMA-IR and HOMA-β homeostasis models rely on basal plasma insulin and glucose measurements to assess insulin resistance and pancreatic β cell activity, respectively." (PMID 39744182, 2024). "T2DM is distinguished by insulin resistance in insulin-responsive tissues and impaired insulin secretion by pancreatic β cells." (PMID 38167106, 2024). "In 3T3-L1 adipocytes with developed insulin resistance, treatment with 1,2-diCA-PC at 125 μM led to increased glucose uptake, indicating improved cellular sensitivity to insulin." (PMID 39339765, 2024). "Overall, these analyses show that TG/HDL is more genetically correlated with measures of insulin resistance than glycemia or insulin secretion." (PMID 39277575, 2024). "T2DM is characterized by progressive insulin resistance, increasing the body’s demand for insulin to maintain the blood glucose level." (PMID 38331889, 2024). "Metformin, a widely used drug for insulin resistance, has been shown to restore insulin signaling in the liver of obese mice." (PMID 39897964, 2024). "Obesity, especially visceral adiposity, is associated with the core defect in the pathogenesis of T2DM; the release of free fatty acids from adipocytes blocks insulin-signaling pathways that lead to insulin resistance." (PMID 38336931, 2024). "METRNL acts as an insulin sensitizer and holds promising potential as a therapeutic target for addressing insulin resistance." (PMID 38681576, 2024). "Thiazolidinedione can improve insulin resistance and improve insulin sensitivity in diabetic patients through FGF21." (PMID 38884020, 2024). "GD is a complex disorder involving disruptions in insulin signaling, mitochondrial dysfunction, chronic inflammation, and oxidative stress, leading to impaired glucose regulation and insulin resistance." (PMID 39519193, 2024). "Pancreatic beta cells are particularly vulnerable to oxidative stress due to their weak anti-oxidative defense mechanisms, which therefore disturbs insulin secretion and exacerbates insulin resistance." (PMID 38302934, 2024). "These pathways, in turn, compromise insulin signaling and lead to the development of insulin resistance in the affected cells." (PMID 39337412, 2024). "Participants assigned to the MARD subgroup had the oldest age of diagnosis (mean: 69.98), moderate BMI (mean: 25.58) and HbA1c (mean: 6.55), and moderate insulin release and insulin resistance status (median HOMA‐β: 51.74, median HOMA‐IR: 2.54)." (PMID 39136497, 2024). "Angiotensin II (Ang-II) inhibits the insulin activation of PI3K signaling, causing insulin resistance." (PMID 38397072, 2024). "Prior to the onset of T2D, insulin resistance leads to hyperinsulinemia as the pancreatic β-cells work to compensate for diminished insulin sensitivity." (PMID 38398503, 2024). "Short-term high-fat high-calorie diet increases the expression of CD14 in skeletal muscle of healthy men accompanied by reduced markers of insulin signalling and development of insulin resistance." (PMID 38331723, 2024). "Recognized for its therapeutic potential, DPIN acts as an insulin sensitizer, enhancing insulin signaling and mitigating peripheral insulin resistance." (PMID 39683582, 2024). "Recent studies indicate a positive correlation between serum leptin levels and insulin resistance, relatively high leptin levels being correlated with lower insulin sensitivity and hyperinsulinemia." (PMID 39518420, 2024). "FGF21 also improves insulin resistance by acting directly on islet β-cells by increasing the number of insulin receptors, inhibiting glucolipotoxicity-induced apoptosis, increasing insulin secretion, and reducing α-cell glucagon secretion." (PMID 39409124, 2024). "This condition typically arises from insulin resistance and/or impaired insulin secretion from the beta cells in the pancreas." (PMID 39734671, 2024). "GRS-T2D primarily captures β-cell function and insulin secretion while the metabolic signature mainly encompassed indicators of insulin resistance." (PMID 38555549, 2024).
Insulin resistance (continued). "Consumption of the HF diet increased fasting plasma insulin concentration (p <0.001), insulin resistance index (HOMA-IR) (p <0.001), and beta cell functional capacity index (HOMA-B) (p = 0.041) compared with the control diet." (PMID 38206915, 2024). "Early stages of insulin resistance can be reversible in OB cats who successfully lost weight, as evidenced by decreased insulin concentrations and the HOMA-IR index." (PMID 39328456, 2024). "In this study, simple surrogate indexes for insulin resistance are assessed that are derived from blood insulin and glucose concentrations under fasting conditions." (PMID 39183975, 2024). "The pathogenesis of GDM remains not fully understood, but insulin resistance and the relative insufficiency of insulin secretion are essential features of GDM." (PMID 38978779, 2024). "In insulin resistance, glucose levels go up after a meal intake and stay high which results in pancreas releasing more insulin, therefore resulting in the positive relation with insulin/glucose and the higher BMI group." (PMID 39852345, 2024). "Insulin resistance is commonly characterized as a decreased sensitivity of bodily tissues to the action of insulin." (PMID 38913047, 2024). "Insulin resistance is the impaired ability of plasma insulin to promote tissue glucose disposal adequately and is accompanied frequently by hyperinsulinemia and glucose intolerance." (PMID 39014506, 2024). "In contrast, type 2 diabetes, the most prevalent form, arises from a combination of insulin resistance and impaired insulin secretion." (PMID 38548784, 2024). "These choices largely depend on the material composition of individual exosomes and are related to insulin resistance and impaired insulin signaling." (PMID 39735643, 2024). "Lifestyle practices that stimulate chronic excess insulin demand and secretion result in lower GLP-1 levels and, therefore, less GLP-1 receptor (GLP-1R) activation, which is associated with increased insulin resistance, obesity, and T2DM." (PMID 39062126, 2024). "As the largest insulin-sensitive tissue, skeletal muscle plays a crucial role in modulating insulin resistance." (PMID 38903580, 2024). "The investigated ultrafast, ultraconcentrated insulin analog formulations aim to extend pump therapy to individuals with significant insulin resistance." (PMID 38542928, 2024). "Both plasma NEFAs themselves, but perhaps more importantly, plasma NEFA levels relative to plasma insulin levels are clear indicators of adipose tissue insulin resistance." (PMID 38786765, 2024). "The HOMA-IR and HOMA-β, which are based on plasma levels of fasting glucose and insulin, have been extensively validated and utilized for measuring insulin resistance and β-cell function." (PMID 38580733, 2024). "Scientists highlight dysfunction of the pancreatic β-cells, impaired insulin secretion, insulin resistance, and the reduction of cellular glucose transport as possible association mechanisms." (PMID 39685901, 2024). "Since HOMA is based off fasting measures of insulin and blood glucose, it primarily reflects liver insulin resistance." (PMID 38797835, 2024). "Type 2 diabetes results from insulin resistance, decreased insulin production, or a combination of both." (PMID 39519540, 2024). "Insulin and insulin-sensitizing drugs have therapeutic value in fighting against insulin resistance, which also affects astrocytes." (PMID 39595866, 2024). "It is noteworthy that physiological insulin resistance occurs during adolescence, marked by a 25–50% decrease in insulin sensitivity." (PMID 39407760, 2024). "Insulin resistance, characterized by suppression of hepatic glucose manufacture and downward sensitivity to insulin-mediated glucose disposal, contributes greatly to the pathogenesis of MetS." (PMID 38279158, 2024).
Insulin resistance (continued). "During the physiological course of pregnancy, due to circulating placental hormones and cytokines that promote insulin resistance, maternal tissue becomes increasingly insensitive to insulin." (PMID 39599657, 2024). "Although the precise mechanism of GDM insulin resistance is unclear, a large number of studies have shown that adipose tissue, as one of the insulin target organs, plays an important role in regulation of insulin sensitivity." (PMID 38791090, 2024). "Supplementation of PSE significantly reduced DM-induced serum insulin and insulin resistance as shown by HOMA-IR and HOMA-B levels in db/db mice, with levels similar to the control mice." (PMID 39683552, 2024). "Insulin resistance (IR) is characterized by insulin sensitivity impairment, as demonstrated by a shift towards higher insulin concentrations on the insulin concentration-effect curve." (PMID 38750553, 2024). "Age-related insulin resistance (IR) is characterized by decreased sensitivity of tissues especially muscle, adipose tissue, the brain, and other organs to insulin." (PMID 39622897, 2024). "Down-regulation of ACE2 is found in patients with COVID-19 that enhances activation of the RAS axis, resulting in decreased insulin and glucose delivery to tissues and impairment of insulin signaling pathways, all of which lead to insulin resistance." (PMID 39253580, 2024). "Body weight contributed the most, followed by homeostatic insulin resistance (HOMA_IR) and fasting plasma insulin levels (Insulin_Fasting)." (PMID 39386475, 2024). "Some of the reports indicate a link between certain selenoproteins involved in the insulin signaling pathway and insulin resistance and glucose metabolism." (PMID 37880477, 2024). "The correlation between hsCRP and HOMA-IR, as well as insulin levels in the blood, is well-documented and underscores the role of inflammation in the pathophysiology of insulin resistance." (PMID 39338165, 2024). "Insulin resistance is defined as an inadequate response of tissues to insulin’s action in the bloodstream and is widely recognized as a key indicator for the development of metabolic disorders such as T2DM and metabolic syndrome." (PMID 39598390, 2024). "Along with T2DM development, pancreas increases insulin secretion to compensate for insulin resistance but later slowly fail to produce enough high amounts of insulin to control blood glucose." (PMID 37880477, 2024). "Insulin resistance, also known as impaired insulin sensitivity, refers to impaired effects of insulin, such as reduced glucose uptake in insulin-sensitive tissues, including skeletal muscles, adipose tissues, and liver." (PMID 38347961, 2024). "CYP2E1 hepatic overexpression increased oxidative stress, increased systemic insulin resistance, decreased insulin signaling in the liver, and increased hepatic fat accumulation." (PMID 40452921, 2024). "T2D is manifested by low insulin secretions from β-cells and peripheral insulin resistance, including high levels of fatty acids, which promote systemic inflammation." (PMID 39065815, 2024). "IF can also reduce insulin resistance by lowering body fat, leading to improved insulin sensitivity and glucose metabolism." (PMID 39533312, 2024). "The hallmark of T2DM is chronic hyperglycemia and abnormal metabolism of carbohydrates, lipids, and proteins, mainly attributed to insulin resistance and insufficient insulin secretion." (PMID 39595541, 2024). "Consuming soybean protein containing isoflavones can control blood glucose levels and reduce insulin resistance, while consuming fermented products can suppress insulin resistance and improve insulin secretion." (PMID 39703396, 2024). "Our study results indicated that administration of EPE to HFD-fed mice displayed activity similar to that of an insulin sensitizer to improve peripheral insulin resistance, including in adipose and liver tissue, and skeletal muscles." (PMID 39329975, 2024).
Insulin resistance (continued). "Overproduction of insulin causes the inactivation of PI3K/Akt/mTOR pathway and finally results in insulin resistance." (PMID 39624846, 2024). "Firstly, insulin resistance reduces the body’s sensitivity to insulin, which promotes the overproduction of glucose by the liver and increases insulin secretion, leading to hyperinsulinemia." (PMID 39744244, 2024). "The comparative evaluation values of fasting insulin, HOMA-IR, and blood insulin-glucose clamp techniques for assessing insulin resistance have been demonstrated." (PMID 40302954, 2024). "Insulin resistance impairs the anabolic effects of insulin on muscle tissue, resulting in decreased protein synthesis and muscle growth." (PMID 38924332, 2024). "GLP-1RAs induce postprandial insulin secretion and improve insulin resistance, which inhibits lipolysis and FFA release in adipose tissue." (PMID 38790963, 2024). "The elevated insulin concentration in the insulin-resistance-inducing protocol led to prolonged activation of ERK, which explains the sustained phosphorylation of ERK1/2 kinase substrates in the control." (PMID 39572596, 2024). "But also systolic blood pressure, total cholesterol, triacylglycerol and fasting insulin levels, a marker of insulin resistance, were lower on HP diets." (PMID 39114126, 2024). "Type 2 diabetes (T2DM) manifests as a metabolic disorder typified by both insulin resistance and insufficient insulin secretion." (PMID 39050247, 2024). "As insulin resistance increased, exogenous insulin administration increased to combat the concurrent blood glucose rise." (PMID 38570742, 2024). "Plasma glutamine concentrations in humans have been shown to be inversely related to insulin resistance and supplementation improves the insulin sensitivity in rodent and human models." (PMID 39682351, 2024). "Insulin resistance diminishes tissue sensitivity to insulin, impairing glucose uptake, while beta-cell dysfunction leads to reduced insulin production and resultant hyperglycemia." (PMID 40226688, 2024). "These M1 macrophages enhance the production of proinflammatory cytokines (such as IL-6, IL-12, and TNF-α), which impede the insulin action on adipocytes, linking inflammation with insulin resistance." (PMID 39273520, 2024). "FPG, Insulin and homeostasis model assessment for insulin resistance (HOMA-IR) are important detection indices of glucose metabolism." (PMID 38633237, 2024). "In muscle tissue, DG species have been shown to impair insulin signaling, leading to insulin resistance." (PMID 38668319, 2024). "Various inflammatory cytokines produced during inflammation, such as TNF-α, IL-1β and IL-6, can affect the function of islet β cells, promote insulin resistance and insulin degradation through specific pathways." (PMID 38225568, 2024). "BCAA levels are very sensitive to changes in insulin concentrations and are correlated with peripheral and hepatic insulin resistance." (PMID 39459592, 2024). "One of the key contributors to the progression of FLHS is insulin resistance, while adiponectin is an insulin-sensitizing and anti-inflammatory agent which plays a vital role in maintaining glucose and lipid homeostasis." (PMID 39305615, 2024). "Obesity and MetS generate oxidative stress due to increased levels of glucose, FFA, and insulin, which increase hyperinsulinemia and insulin resistance." (PMID 38892574, 2024). "Patients with GC in early stages have increased levels of fasting glucose, fasting insulin, total cholesterol, and homeostasis model assessment of insulin resistance (HOMA-IR) compared with healthy patients." (PMID 38339127, 2024). "Insulin resistance refers to a reduced ability of insulin to stimulate glucose utilization, while glucose tolerance remains normal." (PMID 38715070, 2024).